ENO1 (enolase 1)
Diseases named in the same sentence as ENO1 in open-access papers (continued):
Sharing a sentence is not in itself a finding about the gene and the disease.
lung adenocarcinoma (continued). "In addition, another study showed that circ-ENO1 and its host gene ENO1 are upregulated in lung adenocarcinoma and promote the glycolysis process in lung adenocarcinoma through the miR-22-3p/ENO1 axis and affect tumor growth and metastasis." (PMID 33880120, 2021). "The interferon (IFN)-stimulated gene product 15 modification (ISGylated) of ENO1 is found in the human lung adenocarcinoma epithelial cell line A549 and other bacterial 46,62,63, however the function of ISGylated ENO1 remain unclear." (PMID 34671213, 2021). "The study also reveals that circ-ENO1 promotes glycolysis, proliferation, and EMT in lung adenocarcinoma by upregulating its host gene ENO1." (PMID 37599427, 2023). "Within the course of lung adenocarcinoma (LUAD) genesis, there occurs an m6A-dependent aerobic glycolysis, wherein the pivotal determinant for m6A-dependent glycolysis is ENO1 (Enolase 1)." (PMID 38202722, 2023). "MiRNA hsa-mir-30a and lncRNA AC104472.1 constituted regulatory module for lung adenocarcinoma a with TPI1, KPNA2, MET, HSP90B1, P4HB, DSP, CDH1, and ENO1." (PMID 36138770, 2022). "Silencing of circ-ENO1 inhibits glycolysis, cell proliferation, migration and EMT of lung adenocarcinoma." (PMID 33634138, 2021). "We extracted ENO1 and EGFR data from 34 tumors and found that both were notably upregulated in diverse cancer types, especially lung adenocarcinoma and lung squamous carcinoma tissues." (PMID 34627260, 2021). "In lung adenocarcinoma (LUAD), ENO1 promotes tumor development in an m6A-dependent manner." (PMID 37582735, 2023). "In lung adenocarcinoma, UPP1 knockdown via shRNA reduced the protein levels of ENO1 and LDHA in H292 and H1975 cells, whereas overexpression of UPP1 restored the suppression of lactate production, glucose uptake and ENO1/LDHA protein levels induced by 2-deoxy-d-glucose in H1299 cells." (PMID 40804482, 2025).
non-small cell lung carcinoma (29 papers, 2005 to 2025). A group of at least three distinct histological types of lung cancer, including non-small cell squamous cell carcinoma, adenocarcinoma, and large cell carcinoma. "The expression level of ENO1 has been found upregulated in various cancers and is associated with poor prognosis, including non-small cell lung cancer and head and neck cancer." (PMID 34136381, 2021). "The overexpression of ENO1 was associated with clinical stage and recurrence of non-small-cell lung cancer." (PMID 29483925, 2018). "Our previous studies found that ENO1 promoted tumor proliferation, migration, and invasion in non-small cell lung cancer." (PMID 35844805, 2022). "For example, when overexpressed in non-small cell lung cancer cell lines, ENO1 promoted cell glycolysis, growth, migration, and invasion." (PMID 35204345, 2022). "The role of eno1enolase (enolase-1) in non-small cell carcinoma has been widely studied by previous researches." (PMID 33509178, 2021). "They indicate that ENO1 is an upstream signal factor modulating the FAK/PI3K/AKT axis in non-small-cell lung carcinoma (NSCLC) to promote glycolysis, proliferation, migration and invasion of cancer cells." (PMID 34671213, 2021). "ENO1-overexpressed cells were observed in human non-small cell lung cancer cell lines, which can facilitate cell glycolysis, migration, proliferation, tumorigenesis, and invasion." (PMID 34349784, 2021). "The overexpression of ENO1 increased the levels of oncogenic cell cycle regulators in non-small cell lung cancer." (PMID 33643901, 2020). "In this study, we evaluated the prognostic value of anti-ENO1 Ab levels in non-small cell lung carcinoma patients undergoing surgery." (PMID 26551021, 2015). "Circulating levels of anti-ENO1 Ab were assessed in 85 non-small cell lung carcinoma patients before and after surgery, and were correlated with clinical outcome." (PMID 26551021, 2015). "Our previous studies suggest that antibodies against ENO1 (anti-ENO1 Ab) have a protective role in patients with non-small cell lung carcinoma." (PMID 26551021, 2015). "The aim of this study is to examine the levels of alpha-enolase (ENO1) protein in the tumor tissues and peripheral plasma samples obtained from non-small cell lung cancer (NSCLC) patients, and evaluate its potential clinical significance." (PMID 21159241, 2010). "Similarly, alpha-enolase (ENO1) serves as a crucial biomarker in tumor glycolysis, with significantly increased expression in non-small cell lung cancer, and activates FAK/PI3K/AKT pathway, promoting cell glycolysis, proliferation, migration, and invasion." (PMID 39390359, 2024). "Previous study showed that the FAK/PI3K/AKT pathway whose downstream signals could elevate the glycolysis to significantly facilitate non-small cell lung cancer proliferation and metastasis would be activated by upregulated ENO1." (PMID 37741973, 2023). "However, in non-small cell lung cancers, ENO1 is downregulated at the protein level, whereas its expression on mRNA level remains elevated." (PMID 35204345, 2022). "In addition, abnormally high circulating ENO1 levels have also been reported in non-small cell lung cancer." (PMID 35836227, 2022). "Notably, the downregulation of ENO1 has been found in tissue samples from patients with non-small cell lung cancer, and the patients with low ENO1 expression had a worse prognosis." (PMID 33643901, 2020). "This still needs further studies to be confirmed but one could speculate that the ENO1-mRNA level might be of importance in the aggressiveness of neuroblastoma tumours, as seen in non-small cell lung cancer." (PMID 16359544, 2005). "Furthermore, autoantibodies against ENO1 may serve as a promising biomarker for non-small-cell lung carcinoma." (PMID 24099319, 2013). "SPP1 with glycolysis genes (GAPDH, ENO1, LDHA, ALDOA, and TPI1) was also expressed in TAMs in non-small cell lung cancer (NSCLC)." (PMID 38347955, 2023).
non-small cell lung carcinoma (continued). "Interestingly, although ENO1 is reportedly overexpressed in many human diseases and cancers, in non-small-cell lung cancer (NSCLC), ENO1 is downregulated at the protein level even though its mRNA levels remain elevated, suggesting post-transcriptional regulation." (PMID 36139550, 2022).
melanoma (22 papers, 2011 to 2025). A malignant, usually aggressive tumor composed of atypical, neoplastic melanocytes. "Another glycolysis‐regulating enzyme, enolase 1, is dysregulated by multiple checkpoint pathways, and reduced glycolytic metabolism of CD8+ TIL from B16 melanomas was associated with a loss of enolase 1 enzymatic activity when compared to acute T effector cells." (PMID 32508018, 2020). "The previously discussed ascorbic acid also interacts with ENO1 and induces the apoptosis of melanoma cells." (PMID 35204345, 2022). "Our current analysis of clinical melanoma samples in tissue microarrays also showed an increased expression of ENO1 in melanoma cells." (PMID 35204345, 2022). "In clinical analysis, the overexpression of ENO1 in melanoma cells was significantly correlated with advanced clinical stage, presence of metastases in regional lymph nodes, and shorter cancer-specific overall survival and disease-free survival." (PMID 35204345, 2022). "High tumoral immunologic response was predominantly observed in patients with reduced cytoplasmic ENO1 expression—64% of patients with brisk tumor-infiltrating lymphocytes were characterized by low ENO1 reactivity in melanoma cells (p = 0.039)." (PMID 35204345, 2022). "To conclude, our in vitro and clinical models showed that overexpression of ENO1 promotes invasiveness of melanoma cells and correlates with aggressive clinical behavior." (PMID 35204345, 2022). "Overexpression of ENO1 in melanoma cells was significantly correlated with advanced stage of the disease—81% of patients with high expression of ENO1 were classified as pT3 or pT4 (p < 0.001)." (PMID 35204345, 2022). "We also demonstrated high expression of ENO1 in melanoma cell lines compared with normal melanocytes." (PMID 35204345, 2022). "We report significantly higher expression of ENO1 in melanoma cell lines in comparison to normal melanocytes." (PMID 35204345, 2022). "Enhanced ENO1 expression in the cytoplasm of melanoma cells was correlated with unfavorable prognosticators such as Breslow thickness, Clark level, mitotic activity, presence of ulceration, and a worse prognosis in the analyzed cohort of patients." (PMID 35204345, 2022). "The aim of this study was to investigate the prognostic significance of ENO1 in surgical resections from melanoma patients and to assess its expression and enzymatic activity in several melanoma cell lines." (PMID 35204345, 2022). "The aim of the present study was to investigate the prognostic significance of ENO1 in surgical resections from 112 melanoma patients and to assess its expression and enzymatic activity in normoxia and hypoxia in several melanoma cell lines." (PMID 35204345, 2022). "In this research, the overexpression of ENO1 in the melanoma cell lines was correlated with the elevated invasiveness parameters of examined cells." (PMID 35204345, 2022). "Our in vitro research revealed elevated expression of ENO1 protein and ENO1 enzymatic activity in four melanoma cell lines (A375, WM1341D, WM9, and Hs204T)." (PMID 35204345, 2022). "Then, the melanoma was sequentially removed, fixed, sectioned, and reacted with the Anti-ENO1 antibodies or/and fluorescence N3-tag, respectively." (PMID 32013122, 2020). "In summary, we demonstrated for the first time that a covalent inhibitor CA promotes melanoma cell apoptosis through ENO1 silencing." (PMID 32013122, 2020). "The combined antineoplastic effect was reproduced in a mouse xenograft model of melanoma, and the covalent binding of CA to ENO1 was visualized in living tumor cells by an AL-CA probe." (PMID 32013122, 2020). "In summary, these findings demonstrated that CA can arrest the cell cycle via ENO1 and can eventually inhibit melanoma growth." (PMID 32013122, 2020). "In summary, our research confirms that ENO1, as a carcinogen responsible for melanoma, may promote tumor cell proliferation, migration, and invasion through the Wnt/β-catenin pathway, and is a potential target for the treatment of SKCM." (PMID 35925486, 2022).
melanoma (continued). "Furthermore, enhanced ENO1 immunoreactivity in melanoma cells was strongly correlated with high mitotic activity and presence of ulceration (p < 0.001, and p = 0.013, respectively)." (PMID 35204345, 2022). "Moreover, 79% of patients (30/38) diagnosed at stage I according to the AJCC (8th edition) were characterized by low ENO1 immunoreactivity in melanoma cells (p < 0.001)." (PMID 35204345, 2022). "This is in line with our clinical results, since melanoma cases with ENO1 overexpression were strongly correlated with high mitotic index (clinical equivalent of cell proliferation in vitro), and presence of nodal metastases (clinical equivalent of increased cellular migration)." (PMID 35204345, 2022). "To assess ENO1 activity, we performed enzymatic assay on protein lysates from melanoma cells." (PMID 35204345, 2022). "The results demonstrated that CA could arrest the cell cycle through α-enolase (ENO1) and eventually inhibit melanoma growth." (PMID 32013122, 2020). "In addition, both baicalein and baicalin inhibited LDHα expression in Mel586, A375, and B16F0 melanoma cells, and ENO1 expression in SK-MEL-2 and A375 cells, as well as partially suppressed PKM2 expression in SK-MEL-2, A375, and B16F0 tumor cells." (PMID 32984331, 2020). "Moreover, silenced ENO1 resulted in antiproliferative effects, induced a cell cycle arrest in the G2/M/S phases, and triggered apoptosis in melanoma cells." (PMID 32013122, 2020). "Consequently, additional testing of ENO1 as a target for melanoma therapy is necessary." (PMID 35204345, 2022). "In a melanoma preclinical model, CD8+ TILs were found to be metabolically compromised due to a ENO1 post-transcriptional regulation since it was expressed as mRNA and protein level, but ENO1 enzymatic activity was defective." (PMID 33804240, 2021). "We observed that ENO1, PARK7, NPM1 and STMN1 genes expression levels were higher in melanoma cells than in melanocytes and in normal fibroblasts." (PMID 29545914, 2018). "In particular, ENO1 and NMP1 expression levels were higher in all melanoma lines; PTGS3 expression was higher in all cell lines except for Colo853 melanoma cells." (PMID 29545914, 2018). "In addition, uPAR regulates the expression of Enolase-1 (ENO1) and extracellular matrix metalloproteinase (EMPPRIN), which both contribute to the invasive phenotype of melanoma metabolism and glycolysis." (PMID 38339003, 2024). "Analysis of the published data showed that the inhibition of PPARγ decreased the mRNA level of ENO1 in BLCA cells, while Rosiglitazone (a PPARγ agonist) could increase the transcription level of ENO1 in melanoma cells." (PMID 37024456, 2023). "This may be compensatory for the downregulation of its counterpart ENO1 and ENO2, suggesting that the role of enolases needs to be explored in melanoma." (PMID 33937086, 2021). "Interestingly, this expression pattern of ENO1 also positively correlated with estimated population doubling times of examined melanoma cell lines (data not shown)." (PMID 35204345, 2022). "In addition to ENO1, PGAM1 is also highly expressed in melanoma tissues." (PMID 35925486, 2022).
rheumatoid arthritis (20 papers, 2013 to 2025). A chronic, systemic autoimmune disorder characterized by inflammation in the synovial membranes and articular surfaces. "Enolase 1 (enolase alpha) is known as a diagnostic marker of multiple tumors and numerous autoimmune diseases, including rheumatoid arthritis." (PMID 35981048, 2022). "Anti-ENO1 antibody titers were reported to be associated with the severity of periodontitis in patients with rheumatoid arthritis." (PMID 30001173, 2018). "A previous study demonstrated that ENO1 expressed on the surface of monocytes and macrophages contributes to the production of pro-inflammatory mediators in rheumatoid arthritis." (PMID 38675491, 2024). "Rheumatoid arthritis (RA) patients have increased surface expression of enolase-1 (ENO1) on their immune cells, leading to enhanced inflammatory response and promoting tumor angiogenesis." (PMID 38107519, 2023). "In rheumatoid arthritis, ENO-1 can be reattached to the cell surface of monocytes, which induces the CD14-dependent TLR4 signaling to stimulate their pro-inflammatory state." (PMID 38618493, 2023). "In rheumatoid arthritis, ENO-1 was found to reattach to the cell surface of monocytes and stimulate their pro-inflammatory state by inducing the CD14-dependent TLR4 signaling." (PMID 31106201, 2019). "Soluble ENO-1 was found in serum and synovial fluid of rheumatoid arthritis patients and in serum of patients suffering from lupus erythematosus, systemic sclerosis and Alzheimert’s disease." (PMID 31106201, 2019). "For instance, altered levels of ENO-1 has been demonstrated in Alzheimer’s disease, rheumatoid arthritis, systemic sclerosis, type 2 diabetes, systemic lupus erythematosus, hepatic fibrosis, and fungal and bacterial infections." (PMID 31106201, 2019). "On the other hand, Eno1 has a role in cancer aggressiveness, by promoting cell invasion and metastasis through activation of plasminogen into plasmin, as well as in rheumatoid arthritis by promoting the migration of fibroblasts." (PMID 26608260, 2015). "Citrullination of arginine on surface ENO1 is proposed to alter plasminogen binding capacity, leading to decreased fibrinolysis in rheumatoid arthritis." (PMID 23894455, 2013). "Therefore, in this study, we primarily investigated the role of ENO1 in IL-32 synthesis in Con A-mediated PBMCs and RA PBMCs derived from patients with rheumatoid arthritis." (PMID 38675491, 2024). "Interestingly, paracrine ENO1 tends to activate the CD14-dependent TLR4 pathway via functionally binding with TLR4 on monocytes in rheumatoid arthritis (RA)." (PMID 36614179, 2023). "In addition, Ab to ENO1 were detected in sera from patients with early rheumatoid arthritis, and Ab against citrullinated ENO1 was reported to play a role in mouse models of arthritis." (PMID 23894455, 2013). "In the model of rheumatoid arthritis (RA), ENO1 induces early production of pro-inflammatory cytokines and chemokines but delays production of IL-10 to activate the innate immune system." (PMID 36614179, 2023). "The presence of anti-ENO1 autoantibodies is well documented in autoimmune diseases such as rheumatoid arthritis (RA) and autoimmune retinopathy." (PMID 33584813, 2020). "CD109 interacts with enolase 1 (ENO1), which activates p38 MAPK and NF-κB pathways, thus leading to elevated levels of pro-inflammatory mediators involved in rheumatoid arthritis." (PMID 39990858, 2024). "Low smoking rate of our study population may be appropriate to explain substantial number of non-smokers still developing rheumatoid arthritis and supports the role of P. gingivalis and anti-ENO1 in RA, not necessarily linked to smoking." (PMID 26265263, 2015). "Interestingly, paracrine ENO1 tends to activate the CD14-dependent TLR4 pathway via functionally binding with TLR4 on monocytes by a dual mechanism, initially pro-inflammatory and later anti-inflammatory, in rheumatoid arthritis (RA)." (PMID 36614179, 2023).
rheumatoid arthritis (continued). "In conclusion, autoreactive anti-ENO1/mEno1 antibodies that are produced as byproducts during the antibody response to TdEno play a minimal role in the progression of periodontitis in the absence of rheumatoid arthritis." (PMID 30001173, 2018).
bladder cancer (17 papers, 2019 to 2026). "In conclusion, through multi-omics analysis, we found that ENO1 was overexpressed in bladder cancer and associated with poor prognosis, CD8+ T-cell exhaustion and epithelial heterogeneity." (PMID 38273010, 2024). "ENO1 inhibition enhances anti-tumor immunity and sensitizes tumors to immune checkpoint blockade therapies, such as anti-PD-L1, in bladder cancer models." (PMID 41373732, 2025). "Here, we aimed to explore the role of ENO1 in bladder cancer (BLCA) and then construct a signature to predict the prognosis and treatment response of BLCA." (PMID 38273010, 2024). "Another study indicated that the overexpression of ENO1 in bladder cancer (BC) tissue promotes the proliferation and colony formation of BC cells." (PMID 35805203, 2022). "To investigate the involvement of β-catenin on bladder cancer, we over-expressed β-catenin in ENO1 silenced T24 cells." (PMID 31431517, 2019). "Next, we attempted to explore the molecular mechanisms contributing to the oncogenic role of ENO1 in bladder cancer." (PMID 31431517, 2019). "Melatonin induces toxicity of the chemotherapeutic drug gemcitabine in BC cells by silencing the ENO1 upstream factor PPARγ,In a bladder cancer xenograft model, the tumor growth inhibition rate in the melatonin treatment group reached 58%,providing a new perspective for MLT treatment of BC." (PMID 40756978, 2025). "Melatonin inhibits the glycolytic enzyme ENO1 and suppresses bladder cancer." (PMID 40756978, 2025). "ENO1 can also regulate the cell cycle and apoptosis of bladder cancer by β-catenin signaling." (PMID 37497003, 2023). "Besides, GSEA results showed that gene sets including cell cycle, bladder cancer and DNA replication were positively enriched in ENO1 high-expression group among TCGA-BLCA and GSE13507." (PMID 35836227, 2022). "In addition, the correlation between ENO1 expression and bladder cancer survival was analyzed based on the TCGA database." (PMID 31431517, 2019). "Thus, ENO1 up-regulation of β-catenin is critical for the bladder cancer cell proliferation." (PMID 31431517, 2019). "Additionally, n6-methyladenosine enhances the translation of ENO1 by inhibiting PCNA ubiquitination, thereby facilitating the progression of bladder cancer." (PMID 40771930, 2025).